NOXA1 (NADPH oxidase activator 1)
Description:
Functions as an activator of NOX1, a superoxide-producing NADPH oxidase. Functions in the production of reactive oxygen species (ROS) which participate in a variety of biological processes including host defense, hormone biosynthesis, oxygen sensing and signal transduction. May also activate CYBB/gp91phox and NOX3.
Synonyms: P51NOX; NY-CO-31; FLJ25475; SDCCAG31
Tractability: Antibody: UniProt places it where antibodies can reach, with medium confidence; its Gene Ontology location is reachable by antibodies, with medium confidence. PROTAC: ubiquitination databases record sites on it.
Gene: Protein-coding gene on chromosome 9 (137,423,350 to 137,434,451, forward strand). Ensembl gene ENSG00000188747.
Subcellular location: Cytoplasm; Cell membrane
Subcellular location (Human Protein Atlas): Vesicles
Pathways (Reactome):
Signal Transduction: RAC1 GTPase cycle; RAC3 GTPase cycle; RHO GTPases Activate NADPH Oxidases
Disease: WNT5:FZD7-mediated leishmania damping
Gene Ontology:
Molecular function: enzyme binding; protein binding; SH3 domain binding; small GTPase binding; superoxide-generating NADPH oxidase activator activity
Biological process: regulation of hydrogen peroxide metabolic process; regulation of respiratory burst; superoxide metabolic process; superoxide anion generation
Cellular component: NADPH oxidase complex; cytosol; cytoplasm; plasma membrane
Genetic constraint (gnomAD): Loss-of-function variants: 58 observed, 46.14 expected, observed/expected ratio (o/e) 1.26, 90% interval 1.02 to 1.56. The synonymous counts are far from expectation, so gnomAD's model fits this gene poorly and the ratio says little. Missense variants: 668 observed, 501.79 expected, observed/expected ratio (o/e) 1.33, 90% interval 1.25 to 1.42. Synonymous variants: 295 observed, 226.79 expected, observed/expected ratio (o/e) 1.3, 90% interval 1.18 to 1.43.
Homologues: Orthologues: macaque NOXA1 (91% identical), pig NOXA1 (68% identical), dog NOXA1 (66% identical), mouse Noxa1 (59% identical), rat Noxa1 (56% identical), guinea pig NOXA1 (52% identical), tropical clawed frog noxa1 (36% identical), zebrafish noxa1 (18% identical). Paralogues in human: NCF2 (32% identical).
Diseases named in the same sentence as NOXA1 in open-access papers:
NOXA1 is named in the same sentence as 19 diseases in open-access papers, as found by Europe PMC text mining. Sharing a sentence is not in itself a finding about the gene and the disease. The quoted sentences say what the papers report.
colon cancer (3 papers, 2017 to 2019). "NoxA1 regulates activation of Nox1, which can generate ROS and is expressed at high levels in colon cancer cells." (PMID 31412082, 2019). "Finally, NOX1, NOXO1, NOXA1, and p22phox expression are all significantly increased in colon cancers when compared with simultaneously resected, adjacent, histologically uninvolved colonic epithelium." (PMID 28330872, 2017). "Our prior results demonstrated that NOXO1 and NOXA1, in addition to NOX1, are also increased in clinical colon cancer specimens, facilitating the potential for active NOX1 activity." (PMID 28498822, 2017).
Hypertension (3 papers, 2022 to 2024). The presence of chronic increased pressure in the systemic arterial system. "Conversely, genetic deletion of Noxa1 reduces basal and Ang II-induced hypertension and renal oxidative stress." (PMID 36140333, 2022). "Gene silencing of Noxa1 in RVLM effectively alleviated oxidative stress and protected adult rats against l-NAME-induced hypertension." (PMID 36140333, 2022). "Fourth, gene silencing of Noxa1 in RVLM effectively alleviated oxidative stress and protected adult rats against l-NAME-induced hypertension." (PMID 36140333, 2022).
endothelial dysfunction (2 papers, 2021 to 2025). In vascular diseases, endothelial dysfunction is a systemic pathological state of the endothelium (the inner lining of blood vessels) and can be broadly defined as an imbalance between vasodilating and vasoconstricting substances produced by (or acting on) the endothelium. "In conclusion, using an in vivo approach, our study demonstrated that the HIV transactivator protein Tat contributes to HIV-associated endothelial dysfunction via promoting adipose mass loss, and leptin level reduction leading to an upregulated expression of Nox1 and NoxA1." (PMID 34681637, 2021). "To further investigate the mechanisms by which PFKFB3 contributes to endothelial dysfunction and decreased NO bioavailability, we transduced HAECs with NOX1 adenovirus (in addition to its coactivators NOXA1 and NOXO1) and either GFP (control) or wt-, cyt-, or KD-PFKFB3." (PMID 40002359, 2025).
allergic rhinitis (1 paper, 2019). Inflammation of the nasal mucous membranes caused by an IgE-mediated response to external allergens. "Noxa1 acts as a central component of NADPH oxidase (NOX), while Nox1 could affect reactive oxygen species (ROS) production, both of which might contribute to oxidative stress in allergic rhinitis." (PMID 30823938, 2019).
colitis (1 paper, 2014). Inflammation of the colon. "This study demonstrates for the first time that TNFα-induced colitis triggers a marked increase in the expression of key components of the colon-specific NADPH oxidase isoform, NOX1, NOXA1, NOXO1, and p22PHOX." (PMID 25276054, 2014). "Expression of all of the subunits forming the NOX1 system, namely, NOX1, p22PHOX, NOXA1, and NOXO1, was indeed increased in the mouse model of TNFα-induced colitis." (PMID 25276054, 2014). "The observation that the expression of NOX1, NOXA1, NOXO1, and p22PHOX is increased during TNFα-induced colitis is in agreement with previous in vitro studies showing that treatment of T84 colon epithelial cells with TNFα increased NOX1 and NOXO1 expression at the mRNA and protein levels." (PMID 25276054, 2014).
colorectal cancer (1 paper, 2025). A primary or metastatic malignant neoplasm that affects the colon or rectum. "Considering the link between elevated Noxa1 expression and unfavorable outcomes in colorectal cancer patients, along with its loss-of-function mutations, we performed a comprehensive analysis to confirm its role as a standalone prognostic marker." (PMID 40084254, 2025). "This study identified the radioresistance-associated gene Noxa1 from the GEO database, revealing that elevated Noxa1 expression is linked to poor prognosis in colorectal cancer patients." (PMID 40084254, 2025). "Our findings revealed that age (P=3.63×10-6, HR=1.049), T stage (P=1.72×10-2, HR=1.763), and Noxa1 (P=1.52×10-2, HR=1.349) independently predicted colorectal cancer prognosis." (PMID 40084254, 2025). "In a comparative analysis, Noxa1 was primarily expressed in colorectal cancer tissues, Tmem88 was more prevalent in normal tissues, and Larp6 showed no significant expression differences between the two." (PMID 40084254, 2025). "Noxa1 knockdown suppressed the proliferation of radiotherapy-resistant colorectal cancer cells, indicating its potential role as an oncogene in colorectal cancer development and progression." (PMID 40084254, 2025). "In our analyses of colorectal cancer cells, tissues, and organoids, we observed that NOXA1 expression was higher in radioresistant tissues compared to radiosensitive ones." (PMID 40084254, 2025). "We employed GSVA to investigate the relationship between Noxa1 expression and tumor-related signaling pathways, aiming to clarify how Noxa1 influences radioresistance in colorectal cancer." (PMID 40084254, 2025). "The study found that Noxa1 was significantly overexpressed in radiotherapy-resistant colorectal cancer patients, correlating with a poor prognosis." (PMID 40084254, 2025). "Based on the expression patterns of Noxa1 in both radioresistant and radiosensitive cell lines, we speculate that Noxa1 expression may be closely related to both primary and acquired radiation resistance in colorectal cancer." (PMID 40084254, 2025). "Notably, Epithelial-Mesenchymal Transition, hypoxia, angiogenesis, and activated inflammatory responses contribute to the poor prognosis of colorectal cancer, and NOXA1 has been found to be involved in vascular inflammation; thus, the expression of Noxa1 may predict poor prognosis in CRC patients." (PMID 40084254, 2025). "Additionally, ROC and AUC analyses of the TCGA cohort highlighted Noxa1's potential as a standalone prognostic feature, with AUC values of 0.649 at 3 years, 0.565 at 5 years, and 0.510 at 10 years, reinforcing Noxa1's significance in predicting long-term outcomes in colorectal cancer patients." (PMID 40084254, 2025).
gastric tumors (1 paper, 2019). "Notably, expression of Nox1, Noxa1, Cyba encoding p22phox as well as Noxo1 was increased significantly in both mouse models for gastric tumors and gastritis in comparison to wild-type mouse stomach, which suggest the inflammation-dependent activation of the NOX1 pathway." (PMID 30700829, 2019).
glioblastoma (1 paper, 2021). The most malignant astrocytic tumor (WHO grade IV).
pancreatic cancer (1 paper, 2024). "In fact, the analyzed TCGA data on breast, lung, and pancreatic cancer report that HOPS/TMUB1 expression positively correlates with the three genes of the apoptotic response: BAX, BBC3, and NOXA1." (PMID 38731819, 2024).
tumor (6 papers, 2013 to 2025). "In humans, the expression of SLC12A2, FERMT1, NCL, NOP56, and NOXA1 was significantly upregulated in human tumor cells compared to that in normal controls." (PMID 38886341, 2024). "Thus, we hypothesize that Noxa1 overexpression may contribute to radioresistance by chronically elevating ROS production within tumor cells, mediated by antioxidant stress genes induced by the adaptation to high ROS levels." (PMID 40084254, 2025). "Nox1 and its regulators NoxO1 and NoxA1 are expressed greater in human gastric and intestinal adenocarcinomas than in normal gastric mucosa, suggesting that Nox protein activation could be a sign of tumor transformation." (PMID 38742936, 2024).
cancer (5 papers, 2012 to 2025). A tumor composed of atypical neoplastic, often pleomorphic cells that invade other tissues. "NADPH oxidase 1 (NOX1), derived reactive oxygen species and modulated by NOXA1, is crucial in the progression of cancer." (PMID 36925638, 2023). "In fact, we found to the contrary that both NOX1 and NOXA1 were significantly downregulated in B group cancers (NOX1, FC = –2.3, Jorissen cohort; NOXA1, FC = 1.3, both cohorts), which further supports the idea that exogenous, bacterially-derived ROS is a driver in B group CRCs." (PMID 27846243, 2016). "Gene expression analysis also revealed that the expression of pro-apoptotic genes such as Bax, Bak, AIF, NOXA1, CAD, PARP and cytochrome c were increased when cancer cells were treated with gossypol." (PMID 23226540, 2012).
NOXA1 also shares sentences with these, for which no sentence is quoted: Cardiovascular Diseases (1 paper); cystadenoma (1); gastritis (1); glioma (1); invasive breast carcinoma (1); lung adenocarcinoma (1); pancreatic adenocarcinoma (1); pulmonary arterial hypertension (1).